CMSS1 (cms1 ribosomal small subunit homolog)
Synonyms: C3orf26; MGC4308; LOC105374010
Tractability: PROTAC: ubiquitination databases record sites on it; its protein half-life has been measured.
Gene: Protein-coding gene on chromosome 3 (99,817,837 to 100,181,732, forward strand). Ensembl gene ENSG00000184220.
Subcellular location (Human Protein Atlas): Nucleoli; Mitochondria; Nuclear membrane; Nucleoplasm
Gene Ontology:
Molecular function: protein binding; RNA binding
Genetic constraint (gnomAD): Loss-of-function variants: 14 observed, 21.44 expected, observed/expected ratio (o/e) 0.65, 90% interval 0.43 to 1.02. The upper end of that interval is the gene's LOEUF score, 1.02, which puts it in group 4 of 6, group 1 being the genes least tolerant of losing a copy. Missense variants: 167 observed, 182.6 expected, observed/expected ratio (o/e) 0.91, 90% interval 0.81 to 1.04. Synonymous variants: 48 observed, 64.57 expected, observed/expected ratio (o/e) 0.74, 90% interval 0.59 to 0.95.
Homologues: Orthologues: chimpanzee CMSS1 (98% identical), macaque CMSS1 (96% identical), dog CMSS1 (91% identical), guinea pig CMSS1 (86% identical), pig CMSS1 (86% identical), rabbit CMSS1 (85% identical), mouse Cmss1 (82% identical), rat Cmss1 (76% identical), tropical clawed frog cmss1 (56% identical), zebrafish cmss1 (48% identical).
Diseases named in the same sentence as CMSS1 in open-access papers:
CMSS1 is named in the same sentence as 11 diseases in open-access papers, as found by Europe PMC text mining. Sharing a sentence is not in itself a finding about the gene and the disease. The quoted sentences say what the papers report.
bladder cancer (1 paper, 2024). "Ankfn1, Gstt2, Plec, Gphn, Fmo5, Cmss1, Ahnak, Mecom, Slc2a1, Gsta4, Kras, Peak1, and Hmga2 were associated with worse disease-free survival in bladder cancer patients." (PMID 39769061, 2024). "Gstt2, Gphn, Plec Cmss1, Ahnak, Slc2a1, Gsta4, Kras, Peak1, and Hmga2 were associated with worse overall survival in bladder cancer patients, and the association was significant for Gstt2 and Ahnak." (PMID 39769061, 2024). "An 11-gene signature (Hmga2, Peak 1, Kras, Slc2a1, Ankfn1, Ahnak, Cmss1, Fmo5, Gphn, Plec, Gstt2) had the most substantial impact on disease-free survival in bladder cancer patients." (PMID 39769061, 2024).
breast carcinoma (1 paper, 2023). "Such as CMSS1 and ZHX2 in uterine cancer, OSBPL8, FAM214A in breast cancer, TPT1, GPRIN3, and VAV3 in pancreatic cancer." (PMID 37024957, 2023).
hepatocellular carcinoma (1 paper, 2024). A malignant tumor that arises from hepatocytes. "Second, although our results suggest that CMSS1 may be a potential diagnostic and prognostic marker for hepatocellular carcinoma." (PMID 38160346, 2024). "The expression level of CMSS1 in hepatocellular carcinoma tissues was significantly higher than that in normal tissues." (PMID 38160346, 2024). "Then we examined the expression of CMSS1 mRNA in 20 pairs of hepatocellular carcinoma tissues and normal liver tissues adjacent to the carcinoma, and the results showed that the expression level of CMSS1 in the carcinoma tissues was significantly higher than that in the normal tissues." (PMID 38160346, 2024). "Fourth, this study only found upregulated CMSS1 in hepatocellular carcinoma tissues, but did not examine whether altered levels of the gene were also present in the blood." (PMID 38160346, 2024).
latent infection (1 paper, 2025). "Considering the clinically latent infection of FMDV, Cmss1 may differ from other ribosome-related genes and play a vital role in antigen processing and presentation." (PMID 41277842, 2025).
liver cancer (1 paper, 2024). An epithelial or non-epithelial malignant neoplasm that arises from the liver. "It is expected that future studies will further explore the expression level of CMSS1 in liver cancer blood." (PMID 38160346, 2024). "CMSS1 is an RBP, and whether CMSS1 has a regulatory role in liver cancer is unknown." (PMID 38160346, 2024). "Comparative analysis of 369 liver cancer tissue and normal tissue samples from the GEPIA database revealed that the level of CMSS1 mRNA was significantly higher in LIHC than in normal tissues." (PMID 38160346, 2024).
virus infection (1 paper, 2025). "However, intriguingly, the expression level of the ribosomal functional protein CMSS1 significantly increased following virus infection." (PMID 41277842, 2025). "This suggests that Cmss1 may function as a host molecule in antiviral immunity during FMDV infection, limiting viral infection by enhancing antigen presentation." (PMID 41277842, 2025).
cancer (3 papers, 2021 to 2024). A tumor composed of atypical neoplastic, often pleomorphic cells that invade other tissues. "The results suggested that the expression level of CMSS1 mRNA in LIHC was significantly higher in cancer tissues than in normal tissues." (PMID 38160346, 2024). "We first explored the differences in CMSS1 expression in LIHC cancer tissues and normal tissues." (PMID 38160346, 2024). "Previous studies have reported the important role of RBPJ in cancers, indicating that rs9289981 may exert its function by influencing chromatin accessibility and regulating CMSS1 expression." (PMID 36330496, 2022).
tumor (3 papers, 2021 to 2024). "In contrast, the ‘tumor cells 2’ cluster was characterized by genes associated with protein synthesis (Cmss1, Rpph1, Rps12, Lars2, Ncl2), tumorigenesis (Mt-Rnr2, Hmga2, Mab1b) and cell–cell communication (Gphn, Camk1d, Il31ra, Cmss1, Rpph1), which may be indicative of an inflammatory phenotype." (PMID 39769061, 2024). "For both keratinocyte and stem-cell like tumour samples, we found the Filip1l and Cmss1 genes to be differentially methylated in both, human and mouse cSCC." (PMID 34000624, 2021). "The DMR covering intronic regions of Cmss1 and Filip1l is hypermethylated in tumours." (PMID 34000624, 2021).
infection (1 paper, 2025). The state of being infected such as from the introduction of a foreign agent such as serum, vaccine, antigenic substance or organism. "To test this hypothesis, we evaluated the resistance of Cmss1+/+Ifnar–/– and Cmss1–/–Ifnar–/– mice to FMDV infection by injecting 103 PFUs of FMDV subcutaneously into each mouse." (PMID 41277842, 2025).
CMSS1 also shares sentences with these, for which no sentence is quoted: pancreatic cancer (1 paper); uterine cancer (1).